BRAF (B-Raf proto-oncogene, serine/threonine kinase)
Diseases named in the same sentence as BRAF in open-access papers (continued):
Sharing a sentence is not in itself a finding about the gene and the disease.
cancer (continued). "When combined with T cell-activating immunotherapies, BRAF inhibitors, and possibly combinations of BRAF and MEK inhibitors, may augment adaptive immune responses against cancer cells." (PMID 29100459, 2017). "In particular, SW48 and LIM1215 cancer cells, that are wild type (WT) for KRAS, BRAF, NRAS and PIK3CA genes, and GEO cancer cells, that have a KRAS codon 12 mutation, are sensitive to the anti-epidermal growth factor receptor (EGFR) monoclonal antibody cetuximab." (PMID 28978118, 2017). "We sequenced specific exons of 16 cancer-related genes, including the most clinically relevant genes such as KRAS, NRAS, EGFR, BRAF, cKIT, as well as other targetable genes that are known to be somatically altered in solid cancers based on recent scientific and clinical literature." (PMID 28404952, 2017). "Our findings of EDN1 as unique regulator of phenotype heterogeneity maintenance and paracrine protection from BRAF inhibition add a novel feature to EDN1, which is known to be involved in many aspects of cancer development including EMT and chemotherapy resistance." (PMID 28606996, 2017). "Using RNA-seq data obtained from more than 4800 patients and 9 cancer types, we demonstrate that BRAF mRNA is not a single transcript, but rather a pool of 3 transcripts (reference, X1, and X2), which differ in the length and sequence of their 3’UTR." (PMID 28454577, 2017). "The location of the primary tumor, age, sex, histology of cancer cells, presence of lymphatic/perineural invasion, KRAS and BRAF mutation, or EGFR and ERBB2 expression did not significantly influence the success of PDC establishment." (PMID 26909603, 2016). "It should also be mentioned that the discrepancy between the expression of active Ras or BRaf and ERK activity in cancer tissues may be ascribable to the activity of PP1 in each cancer tissue." (PMID 27936234, 2016). "BRAF mutant cancers did not upregulate RNF43 or ZNRF3 expression at the transcript or protein level, unlike the BRAF wild type cancers that attempt to mitigate the Wnt signal." (PMID 27661107, 2016). "We validate the gene activity score using data from the Cancer Cell Line Encyclopedia and drug sensitivity data for five compounds: BYL719 (PIK3CA inhibitor), PLX4720 (BRAF inhibitor), AZD6244 (MEK inhibitor), Erlotinib (EGFR inhibitor), and Nutlin-3 (MDM2 inhibitor)." (PMID 26864072, 2016). "Our observations imply that the discrepancy between the expression of active Ras or BRaf and ERK activity in cancer tissues might reflect the difference in cell density-dependent activity of PSPs." (PMID 27936234, 2016). "In addition, oncogenes, such as KRAS, BRAF, and C-MYC, can stimulate NRF2 transcription and activation in cancer cells." (PMID 27703446, 2016). "So far, the common cancer-driver genes identified in NSCLC include the mutant activations of Kirsten rat sarcoma (KRAS), epidermal growth factor receptor (EGFR), proto-oncogene B-Raf (BRAF), and phosphoinositide-3-kinase, catalytic, α polypeptide gene (PIK3CA)." (PMID 26227959, 2015). "Cancer cells with wild-type KRAS and BRAF show clear changes upon erlotinib treatment, whereas BRAF- and KRAS-mutated cancer cells display a limited change or no significant changes, respectively." (PMID 26168967, 2015). "MEK inhibitors such as CI-1040, PD-0325901, AZD6244, RDEA119/BAY 86-9766, GDC-0973/XL581 and AZD8330/ARRY-424704 which are also being tested clinically target MEK and for a wide variety of cancers, while others such as GSK1120212 target, in addition to MEK, C-Raf, B-Raf V600E and BRAF wild type." (PMID 26404379, 2015).
cancer (continued). "Roles of KRAS and BRAF in other cancers are not discussed here, but have recently been reviewed elsewhere." (PMID 26299805, 2015). "We sequenced 297 loci from 3 cancer-related genes (KIT, PDGFR and BRAF only in wild type GIST)." (PMID 25885906, 2015). "The BRAF mutant cohort was comprised of 120 MSI (56.1%) and 94 MSS (43.9%) cancers." (PMID 25613750, 2015). "We next investigated whether CUDC-101 had any effect on cellular migration because ATC is a highly invasive cancer and the EGFR/RAS/BRAF/MEK/ERK pathway has been shown to regulate cellular migration and epithelial-mesenchymal transition (EMT)." (PMID 25940539, 2015). "Based on our recent observation that BRAF is a client protein of TRAP1, an HSP90 molecular chaperone upregulated in several human cancers including CRC, we evaluated the molecular mechanisms responsible for resistance to apoptosis induced by BRAF activation in human CRCs." (PMID 26084290, 2015). "In addition, BRAFP1 genomic locus was found amplified in the vast majority of cancer types featured in TCGA, including DLBCL, where, as expected by ceRNA partners, BRAFP1 and BRAF expression levels show a positive correlation." (PMID 26442270, 2015). "All three tumors with the SND1-BRAF fusion showed an increased expression of BRAF in cancer cells compared to the adjacent non-involving bronchial epithelium present in the same section which had a basal level staining of the protein." (PMID 25985019, 2015). "The fact that human BRAF-induced PTC is usually at an advanced stage when diagnosed and the lack of knowledge about a possible pre-cancer stage of PTC makes distinguishing the cancer’s causes from its effects difficult." (PMID 26625260, 2015). "We found such examples in BRAF and JAK2 kinases, which are involved in cancer pathologies." (PMID 26322316, 2015). "A comparative approach using the domestic dog as a spontaneous cancer model will provide new insights into the dysregulation of BRAF/MAPK pathway in carcinogenesis and facilitate in vivo studies to evaluate therapeutic strategies targeting this pathway’s molecules for cancer therapy." (PMID 29061943, 2015). "In- and out-degree of BRAF and NRAS genes in TO-DAG network inferred from Cancer Genes list." (PMID 26528329, 2015). "When the mouse BRAF-dependent signature was transposed to the human HG-U133A microarray, we identified 532 genes, potentially indicating the BRAF signature (representing early changes, not related to developed malignant tumor)." (PMID 26625260, 2015). "BRAF mutant/MSS cancers affected patients at a younger average age, more frequently presented at advanced stages and were less commonly proximally located than BRAF mutant/MSI cancers." (PMID 25613750, 2015). "In addition, this case showed carcinoma-specific amplification of 7p (EGFR and BRAF) and 20q (ASXL1, AURKA, and GNAS), which were observed as clonal amplification for the three MSS cases without ERBB2 amplification." (PMID 26336987, 2015). "Sorafenib has been characterized as an inhibitor of BRAF, but has not been approved for BRAF-mutant cancers and poorly inhibits BRAF biochemically." (PMID 24651269, 2014). "Effects of RAF, MEK, and RAF/MEK inhibitors on cancer cell lines with or without RAS, BRAF, PIK3CA, or PTEN mutations." (PMID 25422890, 2014). "When using SNVs only, most such genes were known cancer genes, such as U2AF1, IDH1, and DNMT3A in LAML (FLT3 SNVs cluster within five amino acids), AKT1 and KRAS in BRCA, BRAF and KRAS in COADREAD, IDH1 and PARG (poly (ADP-ribose) glycohydrolase) in GBM, and KRAS in UCEC." (PMID 25348067, 2014). "These BRAF mutant/MSS cancers have not been as well studied, but importantly confer a very poor patient prognosis." (PMID 24651849, 2014). "Whole exome sequencing did not reveal secondary BRAF or RAS mutations but did demonstrate a somatic gain-of-function PIK3CA mutation (H1047R), that has previously been reported in other human cancers." (PMID 23470635, 2013).
cancer (continued). "BRAF and KRAS are upstream activators of the mitogen-activated protein kinase (MAPK) cascade which is commonly hyper-activated in different types of human cancer." (PMID 24139521, 2013). "Binary classification is the process of classifying objects within a group (cancer patients) into two subsets, cancer patients with mutations in KRAS, BRAF or NRAS, and cancer patients without mutations in these genes." (PMID 23991070, 2013). "The paradigm of cancer treatment is rapidly changing from disease-specific type to target-specific approach such as testing the efficacy of BRAF inhibitors in BRAF mutant solid tumors regardless of primary sites." (PMID 22870241, 2012). "Since improving patient survival is the main goal in cancer treatment, further meta-analysis evaluation on the combination of markers involved in this critical network including RAS and PTEN with BRAF seems necessary for future planning in cancer treatment and drug development." (PMID 23056577, 2012). "These proximal, BRAF mut/MSS cancers more commonly arose in females (22/33, 66.7% females; p = 0.01) and there was a non-significant trend toward older age (68.6 years for proximal cancers versus 63.1 years for distal cancers; p = 0.1)." (PMID 23110075, 2012). "Treatment resistance recorded after exposure to PLX4720, had not been anticipated considering studies reporting that BRAF mutant cancers are very sensitive to pharmacological MEK inhibitors and did not correlate to the mutational background of the cells." (PMID 21738740, 2011). "Some cancer cells carrying BRAF mutations are highly sensitive to MEK inhibitors, while cells lacking these BRAF mutations or containing RAS or epidermal growth factor receptor (EGFR) mutations are resistant." (PMID 21411864, 2011). "Furthermore, as the BRAF/MEK/ERK pathway is hyperactive in other malignancies and MEK/ERK are also activated by oncogenic RAS in 30% of all human cancers, the potential to exploit NFAT signalling for therapeutic benefit warrants further investigation." (PMID 19724275, 2009). "Genetic alterations in key components of these pathways, such as EGFR, BRAF, KRAS, PIK3CA, and PTEN, have been well-documented in NSCLC, and our study suggests that CKS1B may play a role in modulating these alterations to drive cancer progression." (PMID 40165937, 2025). "In addition, it may represent the differences in the alternative pathways activated in KRAS mutant cancers, such as PI3K, compared to the BRAF mutant MAPK pathway activation." (PMID 40362630, 2025). "Notably, advanced BRAF p.V600E-mutated carcinomas, including anaplastic and iodide-refractory non-anaplastic carcinomas, can be treated with molecularly targeted therapies, such as dabrafenib (BRAF inhibitor) and trametinib (MAPK inhibitor)." (PMID 41175860, 2025). "However, the cytotoxicity of BRAF and CRAF siRNAs is enhanced when ATG7 is knocked down, suggesting that KRAS-driven metabolic alterations in cancer cells make them particularly dependent on the autophagy pathway as a survival mechanism when the RAF/MAPK pathway is acutely inhibited." (PMID 39272847, 2024). "BRAF MT tumors were significantly more prevalent in the MSI-H population, constituting 62.8% of this subgroup (p<0.001), while All-WT, KRAS MT, and NRAS MT cancer specimens were less frequent, accounting for 21.1%, 15.4%, and 0.7%, respectively (p<0.001 for each)." (PMID 39628993, 2024). "Therefore, multi-kinase inhibition of BRAF and VEGFR-2 is a potential cancer therapy approach." (PMID 38999138, 2024). "However, numerous non-Class I BRAF inhibitors are also in development and have been explored in some cancers." (PMID 39018217, 2024).
cancer (continued). "Notably, this class of RAF inhibitors was effective in suppressing the MAPK pathway only in BRAFV600E-mutant cancer cells and not in BRAF-wild type cells." (PMID 38731852, 2024). "Over 85% of cancers exhibit hyperactive MAPK signaling, which is directly caused by genetic alterations of its upstream activators or components, including RTKs, Ras, and BRAF, or indirectly by those independent of Ras or RAF." (PMID 38277205, 2024). "As to CDKN1A, which codes for the p21 tumor suppressor protein, we unexpectedly revealed lower methylation levels within the proximal promoter and 1st exon alike in carcinomas compared to BOTS, especially when BOTS without the BRAF V600E variant were considered." (PMID 39456618, 2024). "In siliconsilicon analysis, we investigated the binding free energy (ΔG) of Neuropilins, an anti-cancer therapy targeting angiogenesis through the inhibition of vascular endothelial growth factor (VEGF), with various signaling pathways including CDK4, EGFR, RAS, BRAF, PI3K, and PTEN." (PMID 37885828, 2023). "It is currently not entirely known whether targeted BRAF-drug resistance is widespread, or only found pre-existing within a small population of cancer cells." (PMID 37277330, 2023). "The absence of BRAF point mutations other than V595E in this study, and the lack of evidence for recurrent alterations in ARAF and RAF1, is globally consistent with observations in human cancers." (PMID 37079639, 2023). "Furthermore, we also found BRAF inhibitor or MEK inhibitor monotherapy initiated negative feedback loops in RAS mutant cancer cells, leading to dysregulation of MAPK signaling pathway." (PMID 36872366, 2023). "In other cancer types, the interplay between BRAF p.V600E and MSI/dMMR is not observed." (PMID 37190216, 2023). "Thus, DTC is generally characterised by molecular profiling as BRAF-predominant, RAS-predominant or non-BRAF-non-RAS-like, with mutations in BRAF and RAS genes being common in aggressive cancers." (PMID 37207147, 2023). "In addition, subsequent studies found that eosinophils could directly kill BRAF and P5K1940 cancer cells by generation of cytotoxic and apoptotic factors." (PMID 36376448, 2023). "Importantly, however, HT was only a protective factor in patients with BRAF-wild type carcinomas, but not the BRAF-mutant subpopulation." (PMID 37190300, 2023). "Evaluating the in-silico toxicity profile of the other available marketed drugs against the BRAF overexpression cancer such as sorafeniib, TAK-632 our selected antagonist would have the more possibility to reduce the side effects currently possible anti-cancer treatments." (PMID 36267655, 2022). "Considering that AS is common in cancer, aberrant splicing of BRAF might not be the only splicing event related to vemurafenib resistance." (PMID 35883549, 2022). "Overall, the BRAF inhibitors used for cancer could affect wild-type RAF signalling in non-cancerous cells, potentially in unpredictable ways." (PMID 35147166, 2022). "Moreover, the transcripts of genes related to cytotoxicity/killing of cancer cells and immune suppression, but no antigen processing and presentation, the JAK-STAT and IFN-γ signaling were enriched in BRAF-mutated NSCLC." (PMID 36543792, 2022). "Although BRAF inhibitors are efficient in decreasing cell proliferation via the inhibition of the MAPK/ERK pathway, reactivation of this pathway occurs in 80% of BRAF-inhibitor-resistant cancer cells, suggesting that these cells rapidly adapt to MAPK inhibition." (PMID 35053476, 2022).
cancer (continued). "Additionally, the combined targeted therapy, including targeted agents (which were against EGFR, ALK, BRAF, IGF-1R, MET(c-MET), VEGF) and antibody–drug conjugate (ADC), as well as cancer vaccines, was among the top three most effective treatment interventions in this study." (PMID 36361201, 2022). "Because existing drugs can activate RAF signalling in cancer cells through the RAF ‘paradox’, other types of inhibitor are in development for more robust inhibition of RAF kinases (e.g. Type 2 inhibitors and BRAF-PROTAC degraders that target BRAF to the proteosome)." (PMID 36331065, 2022). "Also the in silico studies proved that the docking score of the compound suggests the interaction of the compound which could tightly regulate key target genes controlling cancer like ER, EGFR kinase, EGFR-cSRC, HDAC-2, PARP-1 and BRAF." (PMID 35059624, 2022). "Three cancer-associated SPOP mutants lacking the NLS sequence (ΔNLS-E47K, -S80R, and -W131G) accumulated exclusively in the cytoplasm in punctate patterns similar to those of SPOP-ΔNLS, but these mutants did not colocalize with BRAF." (PMID 36585710, 2022). "Moreover, BRAF mutated cancers with and without PIK3CA mutations are characterized by the absence of KRAS mutations and a lower prevalence of APC mutations than BRAF wild type counterparts." (PMID 36079062, 2022). "Similarly, it has been suggested that BRAF inhibitors induce cancer cell mediated fibroblast differentiation, followed by fibronectin expression leading to AKT/PI3K activation, which abrogates the cytotoxic response to BRAF inhibitors." (PMID 33803675, 2021). "In addition, we subdivided the cancer samples into two groups: (i) tumors that had known clinically relevant mutations in EGFR signaling genes: EGFR, KRAS, NRAS, and BRAF, and (ii) “wild type” tumors that did not have these mutations." (PMID 33748471, 2021). "For example, it has been shown in other cancers that treatment of patients with BRAF-inhibitors in the presence of nonmutated BRAF can actually lead to a paradoxical activation of the pathway via increased RAS-signaling, in particular when RAS mutations are also present." (PMID 33916289, 2021). "For example, the proto-oncogenes K-RAS and BRAF, the mitogen-activated protein kinase (MAPK), the extra-cellular signal-regulated kinase (ERK), the phosphoinositide 3-kinase (PI3K)-PTEN-AKT, and CDK4/6-Rb signaling play essential roles in cancer initiation, promotion, and progression." (PMID 33807122, 2021). "In general, FV-PTCs are clinically indolent RAS-driven tumors, while TCV-PTCs are BRAF-driven cancers with poor prognosis, and therefore no apparent genetic association exist – even though the FV-PTC in our case was BRAF mutated, which is unusual but not entirely uncommon." (PMID 33466206, 2021). "Additionally, more than half of the LGD SNADETs (60%; 3/5) already had KRAS or BRAF alterations, which might result in progression to HGD or carcinoma." (PMID 34584977, 2021). "Although our study is the largest to date to assess WNT regulators in BRAF mutant cancers, we did not have a sufficiently large enough sample size to draw conclusions as to the prognostic implications of genes that are mutated more rarely, such as MEN1 and GNG12." (PMID 32384699, 2020).